HMGB1 (high mobility group box 1)
Diseases named in the same sentence as HMGB1 in open-access papers (continued):
Sharing a sentence is not in itself a finding about the gene and the disease.
Sepsis (continued). "One of these proteins, HMGB1 (amphoterin), has been identified as a late-acting mediator of lipopolysaccharide (LPS)-induced or sepsis-induced lethality in mice." (PMID 24690901, 2014). "HMGB-1 is considered a late mediator of sepsis in animal models and has been correlated with outcome (survivors/non-survivors) in septic patients." (PMID 25328284, 2014). "Much attention has been focused upon HMGB1 as a late mediator of sepsis, but HMGB1 levels are also increased in a number of other acute and chronic inflammatory disorders." (PMID 24600525, 2014). "Taken together, our results suggest that Gu-4 possesses a therapeutic potential in the treatment of sepsis probably via inhibiting the LPS-induced release of HMGB1 from macrophages and via suppressing the pro-inflammatory activity of HMGB1." (PMID 24603876, 2014). "Abundant evidence supports the view that HMGB1 is an important pathological mediator in animal models of several human diseases, including sepsis, hemorrhagic shock, and acute respiratory distress syndrome (ARDS)." (PMID 25029244, 2014). "Rosi was demonstrated to attenuate endotoxin lethality by inhibiting HMGB1 release in a mouse model of sepsis." (PMID 24624334, 2014). "In this experiment, we also used Ethyl pyruvate (EP) as a positive control, which has been demonstrated to prevent animals from lethal sepsis and to function as a HMGB1 antagonist." (PMID 24603876, 2014). "We have previously demonstrated that HMGB1 plays important roles in sepsis-induced myocardial dysfunction and mediates I/R-induced myocardial apoptosis." (PMID 25309129, 2014). "In recent years, growing evidence has demonstrated that HMGB1 plays a critical role in the generation and development of sepsis by acting as a key “late-phase” mediator." (PMID 24603876, 2014). "In sepsis, murine experimental data demonstrated a critical role of HMGB1 as a late mediator contributing to mortality." (PMID 24524027, 2014). "HMGB1 links the immune response with the autonomic nervous system, which regulates the release of HMGB1 and other cytokines during sepsis." (PMID 25870671, 2014). "The findings reported in the present study indicate that EA induces an anti-inflammatory mechanism that reduces TNF, IL-6, nitrite, and HMGB1 production in one of the more widely used rat models for studying polymicrobial sepsis." (PMID 25057275, 2014). "Further detailed investigations need to be done to decipher the intriguing role of CD11b-mediated signaling transduction in the secretion of HMGB1 in the context of sepsis." (PMID 24603876, 2014). "In recent years, HMGB1 has been identified as a critical “late” pro-inflammatory mediator due to its unique secretion pattern and lethal effects in sepsis." (PMID 24603876, 2014). "We have demonstrated that HMGB1 is an important mediator in sepsis-induced myocardial dysfunction; an increase in HMGB1 expression by cardiomyocytes after ischemia/reperfusion contributes to myocardial apoptosis." (PMID 25309129, 2014). "Extracellular HMGB1 has been regarded as a late inflammatory mediator in sepsis and as an early mediator in ischemia-inducible models." (PMID 24924349, 2014). "VIP and urocortin protect from the lethal effect of E.coli and cecal ligation and puncture (CLP)-induced sepsis and this protection is paralleled by a decrease in the systemic levels of high mobility group box 1 (HMGB1)." (PMID 25101851, 2014). "HMGB1 is a well-known late inflammatory mediator in sepsis and it can be released readily from necrotic or damaged cells to serve as a signal for inflammation." (PMID 24708589, 2014). "Recently, TM-α improved the elevated circulating levels of HMGB-1 in patients with sepsis-induced DIC." (PMID 25520842, 2014). "It is interesting that individuals who survive sepsis also demonstrate elevated levels of HMGB1 9,26." (PMID 23808943, 2013).
Sepsis (continued). "Based on clinical studies, recent data have shown that HMGB-1 concentrations in the circulation are elevated in patients with sepsis and trauma, and that this increase correlates with the development of ALI." (PMID 23691208, 2013). "ATF3 can block the processes of innate immune response induced by invading pathogens in the early stage but also regulate the late-acting mediators of sepsis, such as HMGB1." (PMID 24062788, 2013). "HMGB1, is released later than other proinflammatory cytokines, and serves as a “late mediator” of sepsis." (PMID 23874764, 2013). "In this study, we used a rat model of CLP-induced sepsis to examine how HMGB1 influences vascular reactivity 12 and 16 h after peritonitis." (PMID 23532259, 2013). "In conclusion, the present findings indicate that elevated serum C23–45 HMGB1 in murine severe sepsis survivors mediates splenomegaly and leucocytosis with expansion of the Ly6Chigh monocyte subset and primes splenocytes to endotoxin stimulation." (PMID 23808943, 2013). "An anti-HMGB1 mAb, which has previously been shown to attenuate cognitive dysfunction in murine severe sepsis survivors, also attenuates the immunophenotype and splenomegaly." (PMID 23808943, 2013). "In clinical applications, thrombomodulin is also useful in HMGB1-related diseases and conditions such as sepsis because of its anti-HMGB1 properties." (PMID 24244627, 2013). "Administration of neutralizing antibodies that are specific for HMGB1 reduces the lethality of mice with sepsis." (PMID 24065095, 2013). "Recently, HMGB1, a DNA-binding protein, has been recognized as a late inflammatory cytokine during sepsis that is actively released by monocytes and macrophages." (PMID 24453420, 2013). "Neutralizing strategies for HMGB1 inhibition including 'A-box' or anti-HMGB1 antibody treatment, have successfully reduced mortality in mice with polymicrobial sepsis." (PMID 23497622, 2013). "The serum levels of HMGB1 of inpatients suffering from sepsis were significantly higher when compared to the control groups." (PMID 24062788, 2013). "Patients with sepsis have increased high mobility group box-1 protein (HMGB1), a cytokine secreted by immune cells that triggers inflammatory mediators." (PMID 24249974, 2013). "Sera collected from patients with sepsis demonstrated increased levels of HMGB1 compared with sera from healthy controls, with the highest increase of HMGB1 levels in patients who succumbed to the disease." (PMID 23351605, 2013). "We found that even when THI-56 was administered 12 h after CLP, it still reduced the circulating HMGB1 levels, suggesting that this drug can potentially be beneficial in treating sepsis." (PMID 24098466, 2013). "Next, we administered the anti-HMGB1 mAb 2G7 (shown previously to neutralize C23–45 HMGB1) to severe sepsis survivors once daily on days 9, 10 and 11 after surgery." (PMID 23808943, 2013). "Recently, we and others demonstrated that the HO-1/CO system can play a very important role in sepsis through the negative regulation of HMGB1." (PMID 24098466, 2013). "HMGB1, originally described as a ubiquitous nuclear protein, has also been shown to be a late inflammatory cytokine in sepsis." (PMID 23497622, 2013). "The second group of proinflammatory mediators is late-phase cytokines such as HMGB1, which are induced within 16–24 h after the initiation of sepsis." (PMID 24098466, 2013). "Extracellular HMGB1 translocation during inflammatory responses in vivo leads to significantly increased serum levels in patients with arthritis, sepsis and other inflammatory disorders." (PMID 23737912, 2013). "Because increased HMGB1 expression is tightly associated with increased mortality in animal models of sepsis, it should be noted that the administration of THI-56 even 12 h after CLP decreased the circulating HMGB1 levels in CLP mice." (PMID 24098466, 2013).
Sepsis (continued). "We observed that circulating HMGB1 transitioned from predominantly the all-thiol HMGB1 during the second and third weeks after sepsis to the C23–45 HMGB1 during weeks 4–8." (PMID 23808943, 2013). "It is now increasingly evident that HMGB1 plays a major role in several disease conditions such as atherosclerosis, diabetes, arthritis, sepsis, and cancer." (PMID 23766911, 2013). "Administration of recombinant HMGB1 to naive mice induced similar splenomegaly, leukocytosis and splenocyte priming as observed in sepsis survivors." (PMID 23808943, 2013). "The present results strongly suggest that HMGB1 plays an important role in vascular malfunction from an early phase of sepsis." (PMID 23532259, 2013). "The authors concluded that HMGB-1 is a useful prognostic biomarker in sepsis-induced organ failure in patients undergoing PMX hemoperfusion, but formal establishment of the utility of HMGB-1 as a prognostic biomarker still remains to be performed." (PMID 24249974, 2013). "It has been proposed that the attenuation of the circulating levels of HMGB1 has a potential therapeutic uses for the treatment of sepsis." (PMID 24098466, 2013). "The potential therapeutic efficacy of HMGB1 neutralization was investigated in a murine model of SM using an anti-HMGB1 monoclonal antibody (mAb) with previously validated therapeutic benefit in experimental sepsis models." (PMID 23506269, 2013). "Although HMGB1 has been thought to act as a late cytokine mediator of sepsis that activates cells via innate immune receptors, we now know that HMGB1 can also be released early after injury as a damage marker." (PMID 23527291, 2013). "Our results indicate that prolonged elevation of HMGB1 is a necessary and sufficient mediator of splenomegaly and splenocyte expansion, as well as splenocyte inflammatory priming in murine severe sepsis survivors." (PMID 23808943, 2013). "Induction of experimental sepsis in mice by cecal ligation and puncture also results in increased serum levels of HMGB1." (PMID 23351605, 2013). "Pharmacological agents directed against HMGB1 are currently under clinical development, and it will be extremely interesting to explore their efficacy in preventing the complications of severe sepsis survivor syndrome." (PMID 23808943, 2013). "Clinically, several reports have suggested that HMGB1 contributes to a number of diseases including diabetic complications, immune/inflammatory disorders, sepsis, heart failure, rheumatoid arthritis, cystic fibrosis airway disease, and tumor biology." (PMID 23617783, 2013). "During sepsis, TLRs are activated by bacteria and endogenous ligands such as HMGB-1 and HSP70, which are released during cellular stress, and interact with the immune system in the extracellular environment." (PMID 22655058, 2012). "Since apoptosis-related release of the cytokine high mobility group box 1 (HMGB1) by macrophages is a crucial mediator of organ damage in sepsis we determined if HMGB1 release is altered during apoptosis induced by wildtype and NhhA-deficient meningococci." (PMID 22238624, 2012). "We examined the effect of myocardial caPI3K on release of nuclear HMGB-1 in cardiac myocytes in response to CLP sepsis." (PMID 23028587, 2012). "To date, this is the first study that analyses the levels of both of these molecules (the "HMGB-1" ligand and the "RAGE" receptor) in the inflammatory cascade of patients with CAP-associated sepsis." (PMID 22264245, 2012). "HMGB-1 is required for normal cellular function but when released due to necrosis or secretion plays key roles in inflammatory arthritis, sepsis, and acute lung injury." (PMID 22916155, 2012). "It was shown that HMGB1 is a critical cytokine mediator of organ damage in severe sepsis since monoclonal antibodies against HMGB1 protected against organ damage but did not prevent the accumulation of apoptotic cells in the spleen." (PMID 22238624, 2012).
Sepsis (continued). "The knowledge about HMGB1 as an inflammatory mediator gained during the last decade after its rediscovery is mainly based on results from experimental studies, with models of sepsis and endotoxemia in particular." (PMID 22778496, 2012). "A Box is a specific and powerful antagonist of endogenous HMGB1 that has been shown to reverse lethality of established sepsis in a mouse model." (PMID 22962600, 2012). "TLR activation in the kidney during sepsis can be elicited by endogenous ligands called alarmins, such as HMGB1 and HSP70." (PMID 22655058, 2012). "From this point of view, HMGB1 level to a certain extent should be able to reflect the severity of sepsis and infectious disease such as AA, useful to be a diagnostic marker." (PMID 22947457, 2012). "Several lines of evidence suggested HMGB1 as a pathophysiologically active mediator of lung and liver disease as well as sepsis." (PMID 22792152, 2012). "With respect to potential mechanisms for HO-1-mediated protection in sepsis, several studies have demonstrated that circulating levels of HMGB1 contribute to LPS-induced mortality in Hmox1−/− mice." (PMID 22518295, 2012). "Colocalization of high mobility group box-1 (HMGB1) with LC3B-positive structures was observed in neutrophils treated with sepsis serum following the same pattern with TF." (PMID 23029002, 2012). "It has been shown that inhibition the expression and release of HMGB1 can attenuate the organ injury in multiple diseases, especially in severe sepsis." (PMID 22947457, 2012). "In the present study, we discovered that the aqueous extract of MBC effectively inhibited endotoxin-induced HMGB1 release, and rescued mice from lethal sepsis even when given orally at 24 h post the onset of sepsis." (PMID 23193422, 2012). "Transfection of HO-1 or induction of HO-1-derived CO resulted in a significant reduction in the translocation and release of high-mobility group box 1 (HMGB1) in CLP-induced sepsis in vivo." (PMID 22518295, 2012). "In conclusion, HO-1-derived CO significantly attenuated HMGB1 release during sepsis, and this inhibition is a necessary step of CO in protection against sepsis." (PMID 22518295, 2012). "A decade ago, HMGB1 has been rediscovered as a proinflammatory cytokine in sepsis and endotoxemia which, under these conditions, is released downstream of the early cytokine production." (PMID 22778496, 2012). "HMGB1 is an abundant protein present in cellular nuclei and cytoplasm; however, once released into the extracellular milieu, HMGB1 activates inflammatory responses, which can occur in inflammatory diseases such as sepsis and arthritis." (PMID 22778498, 2012). "The aim of this study was to evaluate HMGB-1, RAGE and sRAGE levels in patients with CAP-associated sepsis and determine their possible association with clinical outcome." (PMID 22264245, 2012). "At 12 h after reperfusion, plasma levels of HMGB1, a mediator of endotoxic shock and sepsis, were significantly lower in the fish oil group (0.763 ± 0.32 ng/ml) than in the lipid-free group (1.4 ± 0.63 ng/ml, P = 0.0398)." (PMID 22907722, 2012). "In severe sepsis, high levels of the cytokine high mobility group box 1 (HMGB1) are accumulated leading to lethal organ failure due to epithelial cell dysfunction." (PMID 22238624, 2012). "It was reported that administration of recombinant HMGB1 (rHMGB1) to mice induced sepsis and acute lung inflammation." (PMID 22514737, 2012). "In this study, we demonstrated that mung bean coat (MBC) extract remarkably inhibited endotoxin-induced release of HMGB1 and several cytokines/chemokines in macrophage cultures, and rescued mice from lethal sepsis." (PMID 23193422, 2012). "The redox sensitivity of HMGB1 has particular ramifications for systemic inflammation and sepsis with increased oxidative stress and release of reactive oxygen species (ROS)." (PMID 22778496, 2012).
Sepsis (continued). "The secreted or leaked HMGB1 in the outside of the cellular membrane, as an important inflammatory mediator in late stage sepsis, is highly expressed in various inflammatory diseases and in severe sepsis." (PMID 22947457, 2012). "Recent reports indicated that HMGB1 is a late mediator of sepsis, acting as a key regulator in acute and chronic inflammation." (PMID 23316104, 2012). "In the setting of experimental sepsis, HMGB1 has been defined as a late mediator, as compared to other cytokines, such as IL-6 and TNF-α." (PMID 22778496, 2012). "In the model of sepsis, extracellular HMGB1 can function as an alarm in signal to recruit, alert and activate KCs and other innate immune cells, thereby sustaining a potentially injurious inflammatory response." (PMID 23209806, 2012). "For example, it is reported that cromoglycate, a chromone complex, increases survival during an experimental model of sepsis by inhibiting HMGB1 release." (PMID 22720096, 2012). "HMGB1 is recently identified inflammatory factor which plays a crucial role in the late stage of severe sepsis." (PMID 22947457, 2012). "In contrast to sterile injury, the peak of HMGB1 release during sepsis occurs during later stages of the disease, and the levels of HMGB1 do not always decrease in patients who have recovered from sepsis." (PMID 22778496, 2012). "HMGB-1 induces the release of proinflammatory and procoagulant factors and when injected into mice, leads to the development of clinical features of sepsis and multiorgan dysfunction." (PMID 22264245, 2012). "In animal models of endotoxemia or sepsis, circulating HMGB1 increases to plateau levels between 24 and 36 h, distinguishing itself from TNF and other early cytokines." (PMID 23193422, 2012). "HMGB1 can trigger inflammation and is a late mediator of endotoxemia and sepsis in both animal models and humans." (PMID 21660935, 2011). "RAGE is a receptor for HMGB1, which is an important mediator of the inflammatory response in acute lung injury and sepsis." (PMID 21629785, 2011). "Second, disruption of fetuin-A expression led to significant elevation of serum HMGB1 levels during endotoxemia and sepsis." (PMID 21347455, 2011). "We discovered that HMGB1 is released by activated macrophages, and contributes to the pathogenesis of sepsis." (PMID 21347455, 2011). "First, the time-dependent decrease of circulating fetuin-A levels is accompanied by parallel but contrary changes - a time-dependent increase - of circulating HMGB1 levels in animal model of endotoxemia or sepsis." (PMID 21347455, 2011). "Treatment with nicotine attenuated serum HMGB1 levels, decreased the clinical signs of sepsis, provided significant protection against death and improved survival in "established" sepsis." (PMID 21810260, 2011). "HMGB-1 levels are already known to rise during infections or sepsis, but the key result from the current study is that HMGB-1 levels of the AA group with normal WBC counts were significantly higher than those of the healthy group." (PMID 21507210, 2011). "The delayed HMGB1 release can have lethal consequences in sepsis, as administration of HMGB1-specific antibodies confers significant protection against mortality in endotoxaemia." (PMID 21887276, 2011). "Extracellular HMGB1 translocation during inflammatory responses leads to significantly increased in vivo serum levels in patients with arthritis, sepsis, disseminated intravascular coagulation and other inflammatory disorders." (PMID 21507210, 2011). "ACh and nicotine also reduce the concentration of high mobility group box 1 (HMGB1) protein production by macrophages in sepsis patients." (PMID 21810260, 2011). "We explored further the roles of neutrophils and Akt activation in hyperoxia-augmented lung injury and production of HMGB1, a lethal mediator of severe sepsis." (PMID 21726460, 2011).